EFNB1 (ephrin B1)
Diseases named in the same sentence as EFNB1 in open-access papers (continued):
Sharing a sentence is not in itself a finding about the gene and the disease.
endothelial dysfunction (1 paper, 2025). In vascular diseases, endothelial dysfunction is a systemic pathological state of the endothelium (the inner lining of blood vessels) and can be broadly defined as an imbalance between vasodilating and vasoconstricting substances produced by (or acting on) the endothelium. "In summary, we find that EFNB1 can be targeted by small molecule inhibitors or Fc fusion decoys to prevent endothelial dysfunction and vascular leak." (PMID 41332748, 2025). "Genetic and biochemical assays revealed that NS1-mediated endothelial dysfunction is dependent on C-terminal phosphorylation of EFNB1." (PMID 41332748, 2025). "Reconstitution with the EFNB1 WT construct recovered NS1-mediated endothelial dysfunction, while reconstitution with the phenylalanine substitution mutants of EFNB1 (all six and Y343/344F) did not." (PMID 41332748, 2025). "Limitations of this study include that EFNB1 might not be the only surface-expressed host protein that is required for NS1-mediated endothelial dysfunction, and future studies, especially in in vivo models, are needed to evaluate the relative contribution of candidate proteins." (PMID 41332748, 2025).
esophageal cancer (1 paper, 2025). A primary or metastatic malignant neoplasm involving the esophagus. "For example, the aberrant interaction of epithelial cells within the basal layer at early precancerous stage involves Ephrin-B1 (EFNB1) –Eph receptor B4 (EPHB4) which triggers EMT, leading to esophageal cancer tumorigenesis and progression." (PMID 40248695, 2025).
glaucoma (1 paper, 2024). Increased pressure in the eyeball due to obstruction of the outflow of aqueous humor. "Focusing on the eye, studies in a mouse glaucoma model showed that ephrin B1 led to significant increase in TNFα actions in Müller cells." (PMID 38501146, 2024). "Our goal was to examine ephrin B1, so we choose to focus these studies on retinal Müller cells, as ephrin B1 was localized on Müller cells in glaucoma studies." (PMID 38501146, 2024).
glioblastoma (1 paper, 2021). The most malignant astrocytic tumor (WHO grade IV). "Combined with survival and differential tissue expression analysis, EFNB1 upregulation predicted dismal survival of patients with primary glioblastoma." (PMID 34824583, 2021).
Glucose intolerance (1 paper, 2020). Glucose intolerance (GI) can be defined as dysglycemia that comprises both prediabetes and diabetes. "Together, these data show that mice lacking Efnb1 in POMCprog display altered excitability of POMCprog and develop glucose intolerance that is associated with impaired insulin secretion and impaired parasympathetic nerve activity." (PMID 33253166, 2020).
heart hypertrophy (1 paper, 2023). "Apart from the short axis, P20-P60 CM hypertrophy also depends on the elongation of the CM long axis, which we show here to be independent from ephrin-B1 and which probably depends on the assembly of new sarcomeres at the myofibril extremities, thus contributing to the classical heart hypertrophy." (PMID 36649053, 2023).
Hypertension (1 paper, 2018). The presence of chronic increased pressure in the systemic arterial system. "To assess whether this finding in mice is relevant to human hypertension, we conducted a human genetic study for the association of EPHB6 and its two ligands, EFNB1 and EFNB3, with hypertension in hypogonadic patients." (PMID 30262919, 2018). "To assess the relevance of this phenotype to human hypertension, in this study we investigated the association of SNPs in the EPHB6 gene, and in the genes of its two ligands, EFNB1 and EFNB3, with hypertension in Han Chinese hypogonadic males." (PMID 30262919, 2018). "The deletion of EPHB6, EFNB1 and EFNB3 all result in hypertension in mice, while the deletion of EFNB2 leads to an opposite phenotype, i. e., hypotension." (PMID 30262919, 2018). "Thus, we speculated that EFNB1 and EFNB3 are more relevant to EPHB6 signalling for the hypertension phenotype, and hence they were included in our current hypertension association study." (PMID 30262919, 2018).
lung carcinoma (1 paper, 2025). "As dysregulation of cell-ECM interactions is a common feature in cancers, our study raises the possibility that EGFR and EFNB1 cooperate to regulate cell-matrix adhesion in cancer types where both proteins are overexpressed, possibly including brain, breast, and lung cancers." (PMID 40619000, 2025).
melanoma (1 paper, 2010). A malignant, usually aggressive tumor composed of atypical, neoplastic melanocytes. "As determined by quantitative real-time RT-PCR, the gene expression of ephrin B1 in lumbar (L) 4-5 DRGs was induced 1.8 fold in cancer-induced pain mice compared to normal control mice on day 15 after melanoma transplantation (p < 0.001); however, no change was observed for the Eph B1 receptor." (PMID 20979661, 2010).
neuroblastoma (1 paper, 2017). Neuroblastoma (NB) is the most common solid, extracranial childhood tumor. "FLAG-tagged EphB2 was expressed in the neuroblastoma cell line NG108, treated with either ephrin-B1 or control reagents, and immunoprecipitated." (PMID 28719605, 2017).
oral cancer (1 paper, 2021). "When the clinical data suggested a functional interaction between TUBB4B and Ephrin-B1 regulating survival, we sought to investigate how they cooperate to regulate CSCs in oral cancer." (PMID 35004310, 2021). "Our immunofluorescence analysis and FACS analysis confirmed the enrichment of cells expressing TUBB4B or Ephrin-B1 on the cell surface in sphere cultures of oral cancer cell lines." (PMID 35004310, 2021). "We also observed surface co-localization of TUBB4B and Ephrin-B1 in different oral cancer cell lines." (PMID 35004310, 2021). "Later, we explored its possible cooperation with a signaling protein, Ephrin-B1, the abrogation of which reduces the self-renewal of oral cancer stem cells." (PMID 35004310, 2021). "Here, we provide evidence of TUBB4B-mediated regulation of Ephrin-B1 localization that supports the CSC niche in oral cancer." (PMID 35004310, 2021). "To test out cooperation between TUBB4B and Ephrin-B1 in oral cancer, we initially checked whether the expressions of these proteins are involved in the progression of oral cancer using data retrieved from the TCGA repository." (PMID 35004310, 2021).
orofacial cleft (1 paper, 2017). A disorder of facial skeleton that is characterized by cleft lip and/or cleft palate that result in feeding, speech and hearing problems caused by failures during development. "Associations with KLHL4, EFNB1/PJA1, CPXCR1, TBX22, and BCOR were particularly noteworthy because they are involved in syndromes that feature orofacial clefts." (PMID 28877219, 2017).
Ovarian cyst (1 paper, 2006). The presence of one or more cysts of the ovary. "Hence EphA1, EphA2, EphB2, EphB3, EphB6, ephrin A1, ephrin A5 and ephrin B1 were selected for further analysis in an additional fourteen tumor samples, one ovarian cyst and one ovarian adenoma." (PMID 16737551, 2006).
ovarian serous cystadenocarcinoma (1 paper, 2019). A malignant serous cystic epithelial neoplasm arising from the ovary. "Recently using genome-wide methylation data analysis, five-methylation signature (SLC39A14, PREX2, KCNIP2, CORO6, and EFNB1) were reported as novel independent prognostic biomarker for patients with ovarian serous cystadenocarcinoma, which significantly associated with OS of patients." (PMID 31608277, 2019).
rhabdomyosarcoma (1 paper, 2024). A rare aggressive malignant mesenchymal neoplasm arising from skeletal muscle. "An increased expression of EPHs (EPHB1, EPHB2, EPHB3, and EPHB4) and their ephrin ligands (ephrin-B1 and ephrin-B2) has been implicated in promoting angiogenesis and tumor progression in rhabdomyosarcoma." (PMID 38612645, 2024).
sarcoma (1 paper, 2023). A usually aggressive malignant neoplasm of the soft tissue or bone. "In TCGA sarcoma data, higher expression of ephrin B1 and B2 ligands associated with enhancement of metastatic potential was found." (PMID 37834179, 2023).
small cell lung carcinoma (1 paper, 2021). Small cell lung cancer (SCLC) is a highly aggressive malignant neoplasm, accounting for 10-15% of lung cancer cases, characterized byrapid growth, and early metastasis. "EPHB2, as an EPHB subgroup receptor kinase, could modulate the biological behavior of small cell lung carcinoma through autocrine and/or juxtracrine activation by ephrin-B ligands (EFNB1, EFNB2, and EFNB3) that are expressed in the same or neighboring cells." (PMID 34645436, 2021).
soft tissue sarcoma (1 paper, 2022). A malignant neoplasm arising from muscle tissue, adipose tissue, blood vessels, fibrous tissue, or other supportive tissues excluding the bones. "We have noticed that anti-EPHA2 and anti-EPHB4 as well as anti-ephrin-B1 therapeutic agents have been explored in bone and soft tissue sarcomas, albeit they could have also been tried in the clinical setting." (PMID 35563562, 2022). "Despite our efforts to combine data from laboratory and clinical trials, which are indicative of the suppressive or promoting effect of the EPH/ephrin system, we found ephrin-B1 as the only common molecule from the EPH/ephrin axis being studied among bone and soft tissue sarcomas." (PMID 35563562, 2022).
spina bifida (1 paper, 2022). A congenital neural tube defect in which vertebrae are not fully formed. "We reported that three out of seven spina bifida probands and three out of thirteen family members carried a variant in either EPHA2 (rs147977279), EPHB6 (rs780569137) or EFNB1 (rs772228172)." (PMID 35741713, 2022). "As in the exome dataset of proband SB1A with the EFNB1 variant (rs772228172), four variants were annotated as homozygous (CUBN, COMT, PTCH1 and TRDMT1) and eight variants as heterozygous (CUBN,MTRR, and VANGL1) in the reported spina bifida-related genes." (PMID 35741713, 2022).
Spina bifida occulta (1 paper, 2022). The closed form of spina bifida with incomplete closure of a vertebral body with intact overlying skin. "The rs772228172 variant in ephrinB-type transmembrane ligand, EFNB1 is a C to T base change at 68,049,626 on chromosome X, in an individual with spina bifida occulta, SB1A." (PMID 35741713, 2022).
Teebi hypertelorism syndrome (1 paper, 2011). "The segregation of hypertelorism in three generations suggested a possible diagnosis of Teebi hypertelorism syndrome, but in view of the clinical overlap with CFNS, mutation testing of EFNB1 was arranged." (PMID 21542058, 2011).
type 2 diabetes (1 paper, 2024). "Using protein samples collected from patients with type 1 and type 2 diabetes, we found significantly increased levels of ephrin B1 in the retina." (PMID 38501146, 2024).
ulcer (1 paper, 2013). "In a mouse ulcer model, EphB2 expression was upregulated in the regenerating epithelium and expanded into the isthmus while ephrin-B1 expression was in pit cells and proliferating cells of the isthmus, where stem cells are located and EphB2-ephrin B1 bidirectional signaling is activated." (PMID 23874863, 2013).
viral infections (1 paper, 2025). "EFNB1 and its homologs EFNB2 and EFNB3 have previously been implicated in viral infections as receptors for henipaviruses, including Nipah, Hendra and Cedar viruses." (PMID 41332748, 2025).
X-linked deafness (1 paper, 2024). "First, some X-linked deafness genes were not included in the predefined panel containing 227 HL-related genes, such as RPS6KA3, EFNB1, HDAC8, ARX, and ANOS1, which may cause a negative molecular diagnosis for some patients." (PMID 39272213, 2024).
tumor (30 papers, 2006 to 2025). "Beyond its role in tumor cell behavior, ephrin-B1 is associated with immunological changes in the tumor microenvironment, including increased infiltration of Th2 cells, macrophages, and plasmacytoid dendritic cells (pDCs)." (PMID 41200151, 2025). "They examined the correlation between EFNA3, EFNA4, and EFNB1 expression and immune-related biomarkers, including immune checkpoint-related genes, tumor mutational burden (TMB), and microsatellite instability (MSI)." (PMID 37444544, 2023). "EphB1, the receptor of EFNB1, functioned as a tumor suppressor in AML, EphB1 repression was associated with poor prognosis of pediatric AML." (PMID 35603962, 2022). "High expression of EFNA3, EFNA4, and EFNB1 was associated with tumor progression and worse prognosis in HCC patients." (PMID 36052169, 2022). "This study thoroughly analyzed E-cadherin and associated changes in BC, and reports Ephrin-B1 as a new marker of tumor aggressiveness." (PMID 32292715, 2020). "In brief, it can be concluded that high expression of EFNA3, EFNA4, and EFNB1 may be relevant to more gene mutations and, thus, drive oncogenesis and tumor progression of HCC." (PMID 36052169, 2022). "An association between higher Ephrin-B1 expression and higher stage and tumor grade was found." (PMID 32292715, 2020). "To evaluate the impact of endogenous EFNB1 levels in tumor cells on the antitumor effects of EFNB1-RBD-Fc, we compared the influence of EFNB1-RBD-Fc on MA cells devoid of EFNB1 and MAB1 cells overexpressing EFNB1." (PMID 39864628, 2025). "Most studies suggest that ZIP4 regulates the malignant biological behavior of tumors through zinc ions as a second messenger: however, latest research has identified that ZIP4 itself binds to Ephrin-B1 to regulate tumor metastasis." (PMID 39664563, 2024). "In this sense, cells expressing EphB3 aggregate and adhere, leading to restricted dissemination of EphB-expressing tumor cells in ephrin-B1-positive territories and consequent tumor compartmentalization." (PMID 38651144, 2024). "Interaction with EFNB1 then promoted angiogenesis in endothelial cells, as well as tumor proliferation and migration." (PMID 37091977, 2023). "Subsequent studies showed that that ephrin-B1 controls the distribution and spread of EphB2- and EphB3-expressing tumour cells in the colon, which is overcome during tumour progression by the loss of EphB expression." (PMID 36830852, 2023). "Single studies concerning various cancers showed that Pro-NGF/NGF (nerve growth factor), BDNF (brain-derived neurotrophic factor), Ephrin B1, neuroligin-3, pleiotrophin, semaphorin 4F were involved in the regulation of tumor innervation." (PMID 34277455, 2021). "To detect the role of EFNB1 on tumor-immune activity, we used the TISIDB online tool to obtain the EFNB1-associated immunomodulators." (PMID 34824583, 2021). "Furthermore, we have evaluated the influence of both intrinsic EFNB1 levels within tumor cells and the tumor microenvironment on the antitumor effects of EFNB1-RBD-Fc." (PMID 39864628, 2025). "Furthermore, the efficacy of both glycosylated and nonglycosylated EFNB1-RBD-Fc is influenced by the endogenous EFNB1 levels within tumor cells." (PMID 39864628, 2025). "Importantly, the antitumor efficacy of EFNB1-RBD-Fc is markedly influenced by the tumor microenvironment." (PMID 39864628, 2025). "Additionally, CTShigh TAMs secrete EPHB2, which contributes crucially to tumor-cell stemness via engagement to its receptor EFNB1." (PMID 38460015, 2024). "EFNB1 was correlated with larger tumor size and advanced TNM stage." (PMID 37444544, 2023). "The immune scores (R = 0.31, p = 1.3e-09), stromal scores (R = 0.36, p = 1.4e-12), and ESITIMAT scores (R = 0.35, p = 4.1e-12) showed a significantly positive correlation with EFNB1 expression, while EFNB1 expression was negatively correlated with tumor purity (R = −0.35, p = 4.1e-12) in HCC." (PMID 36052169, 2022).
tumor (continued). "Similarly, high expression of EFNB1 tended to correlate with higher tumor size (T3&T4 vs. T1&T2, p = 0.034) and advanced TNM stage (Stages III & IV vs. Stages I & II, p = 0.028)." (PMID 36052169, 2022). "We discovered that EFNA3, EFNA4, and EFNB1 were highly expressed in HCC tissues compared with normal samples, and the high expression of these genes was associated with tumor progression and vascular invasion and, thus, led to poor prognosis in patients with HCC." (PMID 36052169, 2022). "When taken together, analysis of the clinical data points out that TUBB4 and Ephrin-B1 might have functional cooperation, primarily depending on Ephrin-B1, which affects the tumor properties deciding survival of the patients." (PMID 35004310, 2021). "Moreover, it was observed as the spreading of intestinal EphB2-EphB3-positive tumor cells was hampered by the interaction with surrounding ephrin-B1-expressing normal cells, which led to the reinforcement of E-cadherin adhesion." (PMID 32316101, 2020). "Interestingly, it has recently been reported that tumor cells expressing EphB receptors were restricted to large homogeneous clusters by the ligands ephrin-B1 and ephrin-B2." (PMID 20624275, 2010). "Notably, compared with wildtype EFNB1, the glycosylation-deficient N139D mutant drastically diminishes the sensitivity of tumor cells with chemotherapeutic agents, suggesting the existence of both glycosylation-dependent and -independent effects mediated by EFNB1." (PMID 39864628, 2025). "In short, these findings suggest that some ephrin genes (EFNA3, EFNA4, and EFNB1) are closely related to malignant biological behavior, such as tumor growth, vascular invasion and distant metastasis, and, thus, could be used as promising diagnostic and prognostic biomarkers in patients with HCC." (PMID 36052169, 2022). "Mounting evidence suggests that malignant cells influence the tumor microenvironment (TME) by releasing a plethora of neurotrophic factors, e.g. NGF, BDNF, GDNF, Neuturin and Ephrin B1 to promote axonogenesis, neurogenesis and neural reprogramming." (PMID 39592661, 2024). "Knocking down EFNB1 or EPHB4 also significantly inhibited cancer cell migration and invasion but their overexpressing had the opposite effects in both normal and tumor cells." (PMID 38097539, 2023). "In HCC, the expression levels of EFNA1, EFNA3, EFNA4, EFNB1, and EFNB2 were significantly higher in tumor tissues than in normal tissues." (PMID 36052169, 2022). "We also discovered that EFNB1 was positively correlated with immune, stromal, and ESTIMATE scores but negatively correlated with tumor purity." (PMID 36052169, 2022). "We found that the expression of EFNA1, EFNA2, EFNA3, EFNA4, EFNB1, and EFNB2 was upregulated in the tumor tissues of most cancers compared with corresponding normal tissues." (PMID 36052169, 2022). "The expression of EFNA1, EFNA3, EFNA4, EFNB1, and EFNB2 was significantly increased in tumor tissues compared with normal tissues." (PMID 36052169, 2022). "The results indicated that the expression of tumor cell-derived VEGFA, IGFBP3, EFNA1, EFNB1, IGF2, PDGFA and stroma-derived Angpt2, Cdh5, Esam, Esm1, Icam2, and Tie1 was statistically correlated with that of Pecam1 and elevated in p-EMT TW2.6 tumors." (PMID 34869001, 2021). "In this study, EFNA3, EFNB1, EFNB2, and EPHB2 showed a significant correlation with OS and PFS in LUAD patients and were differentially expressed in tumor tissues and normal lung tissues." (PMID 34645436, 2021). "CD133-positive cells, isolated from the tumor, expressed stem cell markers including nestin, CD133, Ki67, Sox2, EFNB1, EFNB2, EFNB3, Cav-1, Musashi, Nucleostemin, Notch 2, Notch 4, and Pax6." (PMID 22995409, 2012). "Ephrin-B1 is enriched in highly proliferative, dense tumor regions but absent in the fetal cerebellum, reinforcing its tumor-specific function." (PMID 41200151, 2025).